BRMS1 (BRMS1 transcriptional repressor and anoikis regulator)
Diseases named in the same sentence as BRMS1 in open-access papers (continued):
Sharing a sentence is not in itself a finding about the gene and the disease.
Hepatitis (1 paper, 2012). Inflammation of the liver. "In patients with hepatitis, 53.33% exhibited down-regulated BRMS1 expression, while 83.33% of patients without hepatitis showed decreased BRMS1 expression." (PMID 22927944, 2012).
invasive carcinoma of the breast (1 paper, 2017). "This in vivo experiment was performed on 161cases of invasive carcinoma of the breast and BRMS1 mRNA was assessed by Light Cycler quantitative real-time reverse transcription-PCR." (PMID 29254284, 2017).
malignant glioma (1 paper, 2024). A grade III or grade IV glioma arising from the central nervous system. "Moreover, both stRNA-seq and scRNA-seq indicated that BRMS1 + microglia may promote the proliferation and invasion of malignant glioma cells through SPP1/CD44-mediated intercellular interactions." (PMID 39143438, 2024).
metastatic disease (1 paper, 2014). "Therefore, our purpose is to investigate the immunohistochemical expression of BRMS1 in human UM specimens, and to establish if there is an association between its expression and metastatic disease." (PMID 24688598, 2014). "In addition, we intend to establish a possible association between BRMS1 expression and the presence of metastatic disease." (PMID 24688598, 2014).
muscular dystrophies (1 paper, 2019). "BRMS1 and HDAC2 are part of a histone deacetylase complex (HDAC), and the predicted disruption of this pathway indeed fits with studies that linked muscular dystrophies to deregulated HDAC activity." (PMID 31114913, 2019).
neuroblastoma (1 paper, 2026). Neuroblastoma (NB) is the most common solid, extracranial childhood tumor. "However, in contrast with the suppressor role of BRMS1 in adult cancers, BRMS1 was significantly associated with the unfavorable clinical outcomes of neuroblastoma." (PMID 41632777, 2026).
nodular melanomas (1 paper, 2012). "BRMS1 expression levels in superficial spreading and nodular melanomas revealed no obvious differences with regard to score index, number of immunoreactive cells, nor staining intensity." (PMID 22356677, 2012).
pancreatic cancer (1 paper, 2013). "While we do not know whether miR-146 induction by BRMS1 also occurs in PDAC, it is known that miR-146 is overexpressed in pancreatic cancer vs. both normal pancreas and pancreatitis, suggesting that miR-146 has an oncogenic role in pancreatic cancer." (PMID 23718921, 2013).
thyroid carcinomas (1 paper, 2022). "Nuclear factor-κB (NF-κB), which is regulated by BRMS1 and mir-146, is involved in the development of cancer by influencing the proliferative and antiapoptotic signals of thyroid carcinomas." (PMID 35282462, 2022).
tumor (43 papers, 2007 to 2025). "We have recently shown that BRMS1 promoter methylation in the primary tumour was associated with poor DFS while our study on BRMS1 protein expression by immunofluorescence revealed CTCs heterogeneity even in the same patient." (PMID 29069768, 2017). "The association between BRMS1 immunostaining and location, largest tumour dimension, and tumour cell type was determined using the correlation coefficient test." (PMID 24688598, 2014). "Loss of BRMS1 expression correlates with tumor progression, and BRMS1 suppresses several steps required for tumor metastasis." (PMID 22927944, 2012). "Since FN assembly on tumor cell membranes is highly associated with the metastatic potential of tumor cells, it is likely that FN assembly decreases BRMS1 to circumvent metastatic suppression by reducing BRMS1-promoted miR-146a levels." (PMID 33248456, 2020). "Additionally, another discovery made was finding that the expression levels of BRMS1 mRNA were associated negatively with the TNM stage and tumor size, similar to the result between BRMS1 expression and TNM staging." (PMID 28533425, 2017). "However, only staining intensity remained associated with tumor thickness (p = 0.024) and ulceration (p = 0.004) when intensity and percentage BRMS1 immunoreactive cells were analyzed separately." (PMID 22356677, 2012). "Suppression of OPN may be one of the possible underlying mechanisms of BRMS1-dependent suppression of tumor metastasis." (PMID 17227585, 2007). "Moreover, a recent report suggested that BRMS1 was associated with tumor angiogenesis." (PMID 22200669, 2012). "Conversely, other studies suggest that S1P-S1PR2 signaling promotes lung metastasis by downregulating breast cancer metastasis suppressor 1 (Brms1), a key metastasis inhibitor, thereby facilitating tumor progression." (PMID 41511294, 2025). "The spatial relationship between BRMS1 + microglia and tumor cells was inferred from spatial transcriptome RNA sequencing (stRNA-seq) data." (PMID 39143438, 2024). "In contrast, orthotopic tumor growth was only slightly altered, qualifying BRMS1 as a metastasis suppressor." (PMID 37296870, 2023). "In our study, we observed a decrease in the expression of the BRMS1 gene (Breast cancer metastasis suppressor 1) in fibroblasts after treatment with exosomes of tumor origin." (PMID 36012171, 2022). "The migration and the invasion processes of tumor cells can be regulated by many factors, such as BRMS1, E-cadherin, CXCL12, MMP9, Orai1, Stim1, TGF-β, and VEGF." (PMID 29316690, 2018). "Further studies in UM will help to clarify the significance of subcellular localisation of BRMS1 in this particular tumour." (PMID 24688598, 2014). "As a transcriptional co-repressor and E3 ligase, it is plausible that BRMS1, affects tumor metastasis involving a variety of cell signaling pathways in cancer cells." (PMID 24763730, 2014). "It was interesting to see that, in our samples, tumour infiltrating macrophages stained with anti-BRMS1 and their staining intensity was generally higher than in UM cells." (PMID 24688598, 2014). "More specifically, we focused on a select number of SATB1 target genes that are known to participate in tumorigenesis and metastasis (e.g. tumor/metastasis suppressors BRMS1, Kiss1, Claudin-1; tumor/metastasis promoters c-Abl, MMP3, ErbB2 and Snail)." (PMID 24260116, 2013). "Tumor metastasis suppressor genes, including BRMS1, can perform their functions through blocking any one (or more) of these steps; for example, they can sensitize cells to an apoptotic stimulus." (PMID 22927944, 2012).
tumor (continued). "Numerous studies have confirmed that many BRMS1 downstream targets are involved in regulating tumor progression and metastatic behaviors." (PMID 22200669, 2012). "By analyzing the clinico-pathological data from 21 specimens, we found that all three patients with tumor invasion and metastasis exhibited remarkably down-regulated BRMS1 expression." (PMID 22927944, 2012). "By using HCC samples and pair-wise, non-tumorous liver tissues, we found a remarkable down-regulated expression pattern of BRMS1 during tumor progression, indicating the involvement of BRMS1 in HCC." (PMID 22927944, 2012). "Previous studies of BRMS1 in other tumor models revealed a transcriptional regulation role of BRMS1 in OPN expression." (PMID 22927944, 2012). "BRMS1 expression in these tumor tissues is negatively correlated with tumor progression and metastasis." (PMID 22927944, 2012). "Our work demonstrates that expression of osteopontin, a tumor-metastasis promoting protein, is regulated by BRMS1." (PMID 17227585, 2007). "Many genes, such as nm23, KAI1, KISS1, MKK4, BrMS1 and so on, have been identified to have relations with the tumor metastasis." (PMID 17784942, 2007). "One might have expected a different result, as BRMS1 expression has been reported to be correlated with disease-free survival and OS in multiple other tumor entities." (PMID 37296870, 2023). "Moreover, miR-346 induces tumor growth and progression by targeting breast cancer metastasis suppressor 1 (BRMS1), while miR-3910 also promotes progression and migration of the disease via targeting MST1 and inducing the Hippo-YAP signaling pathway." (PMID 37108330, 2023). "However, observations on BRMS1 expression, especially at the mRNA level, and regarding potential interrelationships with tumor and patient characteristics are scarce, which prompted us to investigate this topic further." (PMID 37296870, 2023). "Additionally, BRMS1 lowers the threshold for tumor cells to undergo apoptosis when exposed to stress." (PMID 37296870, 2023). "Phosphorylation of RELA/p65 promotes DNMT-1 to represses BRMS1 tumor metastasis." (PMID 29467412, 2018). "We further evaluated whether there is any association between SOX17, CST6, and BRMS1 promoter methylation in CTC, ctDNA and corresponding primary tumours and the clinical outcome of patients." (PMID 29069768, 2017). "The invasion of tumor cells could be regulated by many factors such as BRMS1, E-cadherin, Keratin19, LOXL2, MMP9, Orai1, Stim1, TGF-β and VEGF." (PMID 27008697, 2016). "The specific contributions and mechanisms through which BRMS1 impacts tumor cell migration and invasion remain unclear." (PMID 24763730, 2014). "Furthermore, the mRNA and protein levels of tumor/metastasis suppressors BRMS1, Kiss1 and Claudin-1 were decreased in MCF-7-shPG cells relative to MCF-7 cells (bottom)." (PMID 24260116, 2013). "The metastasis suppressor, BRMS1, has been demonstrated to cause dramatic regression of metastatic lesions without blocking orthotopic tumor growth." (PMID 22356729, 2012). "Clearly, while BRMS1 may have shared roles in some tumor types, it is apparent that those roles can vary by the cell type from which a tumor arises and also by the tumor microenvironment." (PMID 22356677, 2012). "It was reported that BRMS1 suppression of tumor metastasis is mediated via inhibition of NF-kB and subsequent suppression of the urokinase-type plasminogen activator (uPA), a serine protease that is known to activate the MMPs leading to invasion and metastasis." (PMID 22076152, 2011). "We present evidence that expression of tumor/metastasis promoting OPN is downregulated by BRMS1." (PMID 17227585, 2007). "However, in this study, we demonstrate that it may also inhibit tumor cell invasion by upregulation of the breast cancer metastasis suppressor gene BRMS1." (PMID 26821020, 2016).
tumor (continued). "In addition, BRMS1 has clinical relevance for some tumor types." (PMID 22200669, 2012). "Thus, we identify OPN, a tumor-metastasis activator, as a crucial downstream target of BRMS1." (PMID 17227585, 2007). "There is a growing appreciation for the notion that metastasis-regulating genes, such as KISS1, BRMS1, NME1 or SMAD4, exert their effects at both the tumor and TME level." (PMID 29050279, 2017). "Remarkably, loss of HSP90 function impairs the stability of genes involved in tumorigenesis and tumor maintenance such as HIF-1 alpha, the breast cancer metastasis suppressor 1, BRMS1 or c-Raf and AKT." (PMID 26643555, 2015). "More specifically, knockdown of plakoglobin in MCF-7 cells resulted in the increased mRNA and protein levels of the tumor/metastasis promoters c-Abl, Snail, ErbB2 and MMP3 and the decreased levels of tumor/metastasis suppressors BRMS1, Kiss1 and Claudin-1." (PMID 24260116, 2013). "To demonstrate the regulation relationship between BRMS1 and OPN at the tissue level, we further collected cDNA samples from the other 33 paired HCC tumor specimens to investigate the expression levels of both BRMS1 and OPN." (PMID 22927944, 2012). "Interestingly, the BRMS1-expressing cells elicited a variable expression pattern for VEGF and eotaxin that closely resembled the control PBS injection, suggesting that these two cytokines may be implicated in tumor cell colonization." (PMID 22315691, 2012). "Breast cancer metastasis suppressor 1 (BRMS1) inhibits metastasis of multiple tumor types without blocking tumorigenesis." (PMID 38279176, 2024). "Upregulation of BRMS1 in microglia may lead to M2 macrophage polarization, activate the PI3K/AKT signaling pathway through SPP1/CD44-mediated cell interactions, inhibit tumor cell apoptosis, and promote tumor proliferation and invasion." (PMID 39143438, 2024). "BRMS1 mRNA expression in the leading edge of specimens, potentially the section with the fewest to no tumor cells, was significantly lower than in other areas." (PMID 37296870, 2023). "Publicly available data supported our findings regarding the absence of a correlation of BRMS1 expression with patient and/or tumor characteristics in our and the TCGA datasets." (PMID 37296870, 2023). "Epigenetic alterations, like DNA methylation, in the promoter regions of tumor/metastasis suppressor genes, such as SOX17, BRMS1, and CST6 in EpCAM+ CTCs isolated from individuals with BC, are known to be correlated with enhanced tumor metastasis and poor prognosis." (PMID 35303879, 2022). "We also found strong correlations between BRMS1 mRNA levels and TNM stage and tumor size." (PMID 28533425, 2017). "This is not surprising in that BRMS1 is a metastasis suppressor and has never been shown to be required for tumor initiation or growth." (PMID 24763730, 2014). "A significant difference in BRMS1 expression was revealed between tumor and corresponding normal tissues (P = 4.75E-05, paired Student's t test)." (PMID 22927944, 2012). "In breast, ovarian and NSCL carcinomas, BRMS1 suppresses metastasis by inhibiting growth initiation at secondary sites (i.e., colonization) without preventing primary tumor growth." (PMID 22356677, 2012). "The breast cancer metastasis suppressor 1 (BRMS1) gene was originally identified as a true metastasis suppressor gene in breast cancer cell lines as stable overexpression of BRMS1 suppressed pulmonary metastasis but did not inhibit primary tumor growth." (PMID 22931099, 2012). "BrMS1 prevents disseminated tumor cell growth by restoring the normal gap junction phenotype and maintaining cell-to-cell communication in the primary tumor." (PMID 22481931, 2012).
tumor (continued). "Although there was no obvious difference in the percentage of tumor cells expressing BRMS1 in the cytoplasm, there was a clear decline in staining intensity in metastases as compared to nevi and primary tumors." (PMID 22356677, 2012). "We did not identify any subgroups within the tumor types based on their BRMS1 expression, which indicates that BRMS1 might not be a significant player in these tumors." (PMID 37296870, 2023). "BRMS1 suppresses metastasis of multiple tumor types without blocking tumorigenesis." (PMID 29760585, 2018). "In addition, BRMS1 protein expression level was not considerably related with tumor size and histological grade (tumor size: OR = 0.92, 95%CI = 0.63–1.35, P = 0.673; histological grade: OR = 1.33, 95%CI = 0.87–2.02, P = 0.190)." (PMID 28533425, 2017). "BRMS1 is a predominantly nuclear protein that differentially regulates expression of multiple genes, leading to suppression of metastasis without blocking orthotopic tumour growth." (PMID 29069768, 2017). "Breast cancer metastasis suppressor 1 (BRMS1) is a predominantly nuclear protein that differentially regulates the expression of multiple genes, leading to suppression of metastasis without affecting orthotopic tumor growth." (PMID 22200669, 2012). "Notably, all three samples exhibited remarkably down-regulated BRMS1 expression in tumor tissues, indicating the potential negative correlation between HCC metastasis and BRMS1 expression." (PMID 22927944, 2012). "In addition, metastatic tumor cells can down-regulates metastatic suppressors such as the Breast Cancer Metastasis Suppressor 1 (BRMS1), which belongs to family of metastasis suppressors that suppress metastasis without blocking orthotopic tumor growth." (PMID 22076152, 2011). "This idea is further supported by recent work in the Ogretmen laboratory where it was demonstrated that systemic sphingosine kinase 1-generated S1P regulates metastatic potential, but not tumor S1P, via regulation of tumor S1PR2/Brms1 signaling." (PMID 24970174, 2013). "Conversely, genetic alterations that could enhance tumor metastasis but did not affect primary tumor growth were largely overlooked, until persistent investigators raised awareness of genes that selectively altered metastasis, such as nm23, KISS1 and BRMS1." (PMID 35164808, 2022). "There was heterogeneity in expression of BRMS1 mRNA in LNM and TNM stage, thus random-effects model was performed (LNM: P < 0.001, I2 = 97.2%; TNM stage: P = 0.003, I2 = 88.7%), while showing no heterogeneity in tumor size, and thereby requiring use of a fixed-effect model (P = 0.697, I2 = 0%)." (PMID 28533425, 2017).